MIR28 (microRNA 28)
Synonyms: hsa-mir-28; MIRN28; miR-28
Gene: MicroRNA gene on chromosome 3 (188,688,781 to 188,688,866, forward strand). Ensembl gene ENSG00000207651.
Gene Ontology:
Biological process: miRNA-mediated post-transcriptional gene silencing
Homologues: Orthologues: chimpanzee ptr-mir-28 (100% identical), macaque mml-mir-28 (99% identical), pig ssc-mir-28 (97% identical), guinea pig MIR28 (95% identical), mouse Mir28a (92% identical), rabbit MIR28 (67% identical). Paralogues in human: MIR151A (56% identical), MIR151B (31% identical).
Diseases named in the same sentence as MIR28 in open-access papers:
MIR28 is named in the same sentence as 1 disease in open-access papers, as found by Europe PMC text mining. Sharing a sentence is not in itself a finding about the gene and the disease.
MIR28 shares sentences with these, for which no sentence is quoted: cancer (1 paper).